ZC3H11C (zinc finger CCCH-type containing 11C)
Tractability: No criterion of Open Targets' tractability assessment is met for any kind of drug.
Gene: Protein-coding gene on chromosome 6 (65,301,476 to 65,306,574, forward strand). Ensembl gene ENSG00000214558.
Subcellular location (Human Protein Atlas): Nuclear speckles
Gene Ontology:
Molecular function: metal ion binding
Biological process: poly(A)+ mRNA export from nucleus
Homologues: Orthologues: macaque ZC3H11A (93% identical), dog ZC3H11A (85% identical), mouse Zc3h11a (75% identical), tropical clawed frog zc3h11a (38% identical), zebrafish zc3h11a (35% identical). Paralogues in human: ZC3H11B (99% identical), ZC3H11A (93% identical), ZC3H11D (11% identical).
Diseases named in the same sentence as ZC3H11C in open-access papers:
ZC3H11C is named in the same sentence as 1 disease in open-access papers, as found by Europe PMC text mining. Sharing a sentence is not in itself a finding about the gene and the disease.
ZC3H11C shares sentences with these, for which no sentence is quoted: influenza infection (1 paper).